KDM1A (lysine demethylase 1A)
Diseases named in the same sentence as KDM1A in open-access papers (continued):
Sharing a sentence is not in itself a finding about the gene and the disease.
cancer (continued). "To gain insight into all correlations and clinical valorization of GADD45B/LSD1 in HCC, we investigated the mRNA levels of GADD45B and KDM1A genes in HCC cells by using Cancer Cell Line Encyclopedia dataset." (PMID 37250145, 2023). "Currently, numerous irreversible KDM1A (LSD1) inhibitors have been identified and among them TCP, ORY-1001 and SP2509 are now evaluated in clinical trials as potential cancer treatments." (PMID 36968588, 2023). "Another mechanism of EMT regulation via histone modification is by LSD1 (KDM1A), which is overexpressed in various cancer types." (PMID 37394580, 2023). "The lysine-specific histone demethylase 1A (KDM1A, also named LSD1 or AOF2), a histone demethylase, is involved in many cancers." (PMID 36941992, 2023). "LSD1, also known as Lysine Demethylase 1A (KDM1A), has been detected as an important biologically validated epigenetic target for cancer therapy." (PMID 36154607, 2023). "In this study, we uncover a mechanism by which KDM1A regulates growth and sensitivity to sorafenib in HCC cancer cells." (PMID 35970393, 2022). "Novel targets for cancer therapy have been identified and a methylase (KMT6A/EZH2), which produces the repressive H3K27me3 mark, and a demethylase (KDM1A/LSD1), which demethylates the active H3K4me2 mark, are now under clinical evaluation." (PMID 35406676, 2022). "Additionally, DFS (disease-free survival) was analyzed and showed that 4 cancer types with high KDM1A were positively related to poor prognosis, including ACC (p = 4.2e − 05), LIHC (p = 0.021), KICH (p = 0.026), and LGG (p = 0.017), and low KDM1A was associated with poor DFS for KIRC (p = 0.015)." (PMID 34925656, 2021). "In TCGA, a high KDM1A mRNA level correlated significantly with a high TIL percentage, low fraction of CD8+T cells, high fraction of CD4+T cells and high level of cancer/testis antigens (CTAs) (p = 0.039, 0.038, 0.012, 0.009, respectively)." (PMID 33799951, 2021). "Another strategy involves dual inhibition of both histone deacetylases (HDAC) and KDM1A with 4SC-202 which targets HDAC1, 2, 3, and KDM1A and has been shown to inhibit the stem-related properties of cancer cells reducing their viability." (PMID 34220955, 2021). "Histone lysine-specific demethylase 1 (LSD1/KDM1A) has been considered as an important and promising anti-cancer target." (PMID 34235156, 2021). "However, the role of KDM1A in other cancers remains unknown." (PMID 34925656, 2021). "This interaction between nuclear methylation and HIF1 signaling was also demonstrated to occur via FAD (vitamin B2) regulation of KDM1A, where FAD regulated HIF1A stability in a KDM1-dependent fashion in cancer cells." (PMID 30809153, 2019). "As previously reported, overexpression of KDM1A and KDM2A in NSCLC cells increases cell proliferation and invasiveness and promotes cancer metastasis." (PMID 29619118, 2018). "We compared the mean expression of lysine-specific demethylase (KDM) genes to the expression of LSD1 (KDM1A mRNA) and additional selected cancer markers observed to be similarly regulated." (PMID 29088714, 2017). "To investigate crosstalk between KDM1A and DNMT in cancer cells, we took advantage of previous observations on mouse ES cells, where DNMT1 has been shown to associate with KDM1A." (PMID 27449289, 2016). "The fact that both DNMT1 and KDM1A have been found, independently, to promote cell cycle progression, including through a replication barrier, suggests that crosstalk between histone demethylation and DNA methylation could be essential in enabling cancer cells to overcome cell cycle checkpoints." (PMID 27449289, 2016). "KDM1A and STAT3 were significantly higher in cancer cells than in normal cells." (PMID 40246812, 2025). "Similarly, elevated polyamines inhibit lysine demethylase 1A (KDM1A), resulting in activation of a cancer cell stemness transcriptional program." (PMID 40603833, 2025).
cancer (continued). "Recent evidence of colistin's anticancer activity, mediated through inhibition of intracellular lysine-specific histone demethylase 1 (LSD1/KDM1A), suggests that dextrin-colistin conjugates could be used to treat cancer cells, including AML." (PMID 38868592, 2024). "In fact, published studies utilizing knock down approaches, blockage of PELP1 downstream signaling utilizing a KDM1A inhibitor, and reducing PELP1 expression using a CDK inhibitor Roscovitine, demonstrate the benefit of targeting PELP1 in reducing cancer progression." (PMID 37199805, 2023). "KDM1A exhibits the ability to demethylate H3K4me1/2 or H3K9me1/2 to repress or activate transcription and mediate progression of some cancers by demethylating nonhistone proteins." (PMID 33799951, 2021). "KDM1A expression was a positive correlation with pathological stages in 4 cancers, including LIHC, HNSC, SKCM, and OV, but not others." (PMID 34925656, 2021). "In addition, we illustrated that the positive correlation between KDM1A expression and MDSC infiltration happened in most cancers." (PMID 34925656, 2021). "We further analyzed the potential correlation of KDM1A DNA methylation with the prognosis of different cancers via MethSurv and MEXPRESS approach, and the results showed that hypermethylation of KDM1A is positively correlated with good prognosis in most tumors." (PMID 34925656, 2021). "On the other hand, the regulation of KDM1A in cancer progression is mediated by the demethylation of nonhistone proteins." (PMID 34307695, 2021). "Several of the epigenetic enzymes targeted by these drugs, such as DNA methyltransferases (DNMTs), histone deacetylases (HDACs), the histone demethylase (HDM) LSD1/KDM1A and the histone methyltransferases (HMTs) EZH2 and G9A, play a role in the transcriptional repression of TEs in cancer cells." (PMID 34968293, 2020). "We also used Gene Expression Omnibus (GEO) profiles (GSE19804) to analyze KDM1A expression and confirmed that the expression of KDM1A was higher in cancer tissues than in non-tumors." (PMID 30568590, 2018). "Lysine-specific demethylase 1 (LSD1, also known as KDM1A, AOF2, BHC110 or KIAA0601) is one of a number of epigenetic regulators that have recently emerged as candidate therapeutic targets in cancer." (PMID 29590629, 2018). "Intriguingly and in contrast to what is observed in ES cells, KDM1A depletion in cancer cells was found not to trigger any reduction in the DNMT1 or DNMT3B protein level or any change in DNA methylation." (PMID 27449289, 2016). "Contrary to published data reported in ES cells, DNMT1 methylation and stability is not influenced by the decreased of KDM1A in cancer cells." (PMID 27449289, 2016). "This study establishes a mechanism by which KDM1A promotes cancer metastasis in NSCLC cells, and we suggest that KDM1A may be a potential therapeutic target for NSCLC treatment." (PMID 27058897, 2016). "Having observed that DNMT1 and KDM1A co-localize at replication foci in NIH3T3 cells, we wondered whether they interact directly in cancer cells." (PMID 27449289, 2016). "Several connexions between DNA methylation and histone modifications have been described in cancer, but the link between KDM1A and DNMTs in cancer cells has not been explored." (PMID 27449289, 2016). "We next examined whether KDM1A knockdown might affect levels of DNMT1 and/or DNMT3B transcripts in cancer cells." (PMID 27449289, 2016). "Among the 148 mutation carriers, the lowest median age at diagnosis was for KDM1A at 49 years (range 45 to 59) and the highest was for DIS3 at 62 years (range 37 to 67 years), significantly younger than the median age at diagnosis of MM (69 years) in SEER cancer stats." (PMID 41495781, 2026). "Lysine demethylase 1A (KDM1A), which has been well studied, has both histone and non-histone targets, which were nicely reviewed by Cai and colleagues, 2024, who also summarized current inhibitors in clinical trials for all cancers." (PMID 40805121, 2025).
cancer (continued). "To date, there is no comprehensive study on the prognostic significance of KDM1A in pan-cancer." (PMID 34925656, 2021). "LSD1 (protein lysine-specific histone demethylase 1A), also named KDM1A, demethylates a range of important cancer-causing nonhistone proteins, including DNMT1, HSP90 and STAT3, and could be a promising target." (PMID 32708698, 2020). "KDM1A may represent an important therapeutic target for NSCLC and other cancers." (PMID 27058897, 2016). "Lysine Specific Demethylase (LSD1 or KDM1A) in complex with its co-repressor protein CoREST catalyzes the demethylation of the H3 histone N-terminal tail and is currently one of the most promising epigenetic targets for drug discovery against cancer and neurodegenerative diseases." (PMID 24274367, 2013). "Knock-down and overexpression studies in cancer cell lines suggest that Usp22 may promote cancer through the positive regulation of well-known oncogenes including BMI1, c-MYC, SIRT1, cyclin B1, and KDM1A, mainly through the regulation of cell cycle progression." (PMID 34503086, 2021). "Furthermore, we have observed no decrease in DNMT1 protein in KDM1A-knockdown cancer cells, suggesting that KDM1A might not affect the stability of the DNMT1 protein in the context of cancer." (PMID 27449289, 2016). "This analysis also revealed a number of epigenetic oncogenes (KDM1A, HDAC1, TDG) and tumor suppressors (KAT2B, PRDM5, DUSP1, EYA4) which did not correlate significantly with any of the others, suggesting that these may affect cancer DNAm patterns independently of each other." (PMID 26169266, 2015). "Thus, the interplay of KDM5D and KDM1A may have resulted in the clinicopathological findings of the present study, because the final effect on chromatin structure and genome function in most cancers is not strictly dependent on one histone modification." (PMID 37974379, 2024). "Through multiple analyses, we observed a statistically positive correlation between KDM1A expression and CAF in most cancer types, but a negative correlation in THYM." (PMID 34925656, 2021). "Moreover, neutrophil infiltration was positively correlated with KDM1A expression in multiple tumors from various algorithms, whereas other myeloid cells, such as macrophages and dendritic cells, showed no obvious correlations with KDM1A in cancer types via different algorithms." (PMID 34925656, 2021). "Our results show that KDM1A knockdown in cancer cells increases global H3K4 dimethylation, while in KDM1A-knockout ES cells, no change in H3K4 dimethylation was seen." (PMID 27449289, 2016). "Likewise, KDM1A appeared not to influence the methylation level of the subtelomeric repeats D4Z4 and NBL2, whose methylation is frequently dysregulated in cancer." (PMID 27449289, 2016). "However, it is not clear whether KDM1A can also regulate specific TIMP genes and thereby promote cancer metastasis." (PMID 27058897, 2016).
tumor (445 papers, 2011 to 2026). "KDM1A (LSD1) is overexpressed in primary tumor lesions and correlates with an increased risk of recurrence." (PMID 38254784, 2024). "The effect of KDM1A inhibition on the tumor microenvironment caused by NCL-1 as well as KDM1A small molecule inhibitors that are already more advanced and currently under investigation in early clinical trials warrants further investigation." (PMID 39458030, 2024). "In adrenal lesions of these patients, the loss of histone demethylase KDM1A, which acts in this context as a tumor suppressor gene, reduces the condensation of chromatin with subsequent overexpression of GIPR." (PMID 37298217, 2023). "Our results show that KDM1A inhibition unleashes an antigen-independent killing mechanism via the FAS-FASL axis to make tumor cell variants that partially or totally suppress antigen expression susceptible to CAR T cell therapy." (PMID 34771652, 2021). "The functional diversity of KDM1A originates from its complex structure and interactions with transcription factors, promoters, enhancers, oncoproteins, and tumor-associated genes (tumor suppressors and activators)." (PMID 29921310, 2018). "Overall, our findings not only indicate that KDM1A is a promising target for ESCC patients at early stages but also provide novel mechanistic insights into its spatial regulation of STING-associated anti-tumor immunity in sTILs to drive the oncogenic processes in ESCC." (PMID 39638799, 2024). "In summary, the findings of this study not only indicate that KDM1A is a promising target for ESCC patients at early stages but also provide novel mechanistic insights into its spatial regulation of STING-associated anti-tumor immunity in sTILs to drive the oncogenic processes in ESCC." (PMID 39638799, 2024). "This likely reflects KDM1A tumor suppressor role in regulating germinal center B-cell differentiation, where loss-of-function accelerates plasma cell expansion and shortens MGUS-to-MM latency." (PMID 41495781, 2026). "In vitro, dual inhibition of PRUNE-1 and LSD1/KDM1A promoted differentiation and altered the tumor microenvironment in MB cells, identifying a potential therapeutic approach for group 3 MB tumors." (PMID 40556679, 2025). "KDM1A expression is often increased in PCa, and preclinical studies in cell lines have demonstrated that inhibiting KDM1A leads to anti-tumor activity." (PMID 38254784, 2024). "Depletion of HNF4A-liver-TEs and KDM1A knockdown exerted notable suppressive effects on tumor cell growth, consistent with the observed effects in conventional HCC cell lines." (PMID 38965210, 2024). "Research has shown that the high expression of KDM1A promotes the proliferation and invasion of HCC cells and is associated with tumor aggressiveness and poor prognosis." (PMID 39749193, 2024). "A multi-omics study revealed that KDM1A is highly overexpressed in up to 51.5% of all 33 analyzed tumor types and predicts poor survival in 24.2% of them." (PMID 39638799, 2024). "Additional epigenetic regulators, like the human silencing hub (HUSH) complex and lysine demethylase 1A (KDM1A), employ a similar TE-dependent mechanism to impact tumor development." (PMID 38965210, 2024). "NCL-1 most likely inhibits KDM1A-orchestrated tumor angiogenesis and/or vascularization in the tumor in addition to its effects on tumor cell renewal." (PMID 39458030, 2024). "Subsequently, we analyzed tumor samples from these experiments and observed an increase in the H3K4me1 within liver-TEs following KDM1A inhibition." (PMID 38965210, 2024). "Based on the all results, we found that circRANBP17 positively modulated KDM1A through binding to miR-27b-3p, thus regulating tumor progression in NB." (PMID 36941992, 2023).
tumor (continued). "Accordingly, pharmacologic KDM1A inhibition demonstrated efficacy in reducing tumor growth and progression in vitro and in vivo." (PMID 37385999, 2023). "Upon shRNA-induced knockdown of KDM1A, a moderate but significant decrease in cell viability was detected in all tested primary tumor-derived CRC-SCs (n = 4) and HCT116 cells, with more than 20% inhibition of cell viability over a timeframe of 9 days." (PMID 37385999, 2023). "Preclinical studies of seclidemstat showed significant inhibition of tumor growth in neoplasms with KDM1A overexpression." (PMID 37873808, 2023). "Although either KDM1A knockdown or doxorubicin treatment alone resulted in partial tumor regression, combined KDM1A knockdown with doxorubicin treatment was able to further inhibit tumor growth." (PMID 35198054, 2022). "In a subcutaneous synergistic mouse tumor model, KDM1A is a potent inhibitor of anti-tumor immunity, and its ablation activates the type I interferon along with CD8 + T-cell infiltration." (PMID 36048239, 2022). "The CKG not only automatically connected LSD1/KDM1A to tranylcypromine, the drug approved by the tumor board for our patient, but also indicated trans-2-phenylcyclopropylamine, a known potent inhibitor of the demethylase, as another treatment option." (PMID 35102292, 2022). "Lysine (K)-specific demethylase 1A (LSD1/KDM1A) is a lysine demethylase that was identified as a promising therapeutic target in tumor therapy through functioning on histones H3K4me1/2 and H3K9me1/2." (PMID 36376832, 2022). "In HYGH, our results showed a significant correlation between high KDM1A expression and a high tumor-infiltrating lymphocyte (TIL) percentage (p = 0.004)." (PMID 33799951, 2021). "The reversible KDM1A inhibitor CC-90011 has been found to induce cellular differentiation exhibits anti-tumor efficacy in vitro and in vivo in AML and SCLC." (PMID 34220955, 2021). "Together, all the results showed that miR-329-3p inhibits HCC tumor growth by receding immunosuppression through downregulating KDM1A which results in PD-L1 reduction." (PMID 34307695, 2021). "Anticancer immune responses according to KDM1A expression were analyzed through distributions of tumor-infiltrating lymphocytes such as CD8+T cells and CD4+T cells." (PMID 33799951, 2021). "TIMER2.0 was used to detect the differential expression of KDM1A between tumor and corresponding normal tissues from TCGA." (PMID 34925656, 2021). "miR-101 acts as tumor suppressor by targeting the 3′ UTR of KDM1A, thereby reducing tumor growth and progression." (PMID 34679437, 2021). "Our findings suggested that KDM1A-mediated FAS upregulation at the tumor site is the mechanism behind enhanced CAR T cell efficacy." (PMID 34771652, 2021). "Some authors reported significantly higher mRNA and protein expression in ESCC compared with the corresponding normal oesophagus and precancerous tissues, whereas Chen and collaborators observed decreased KDM1A expression in tumour tissue." (PMID 32429269, 2020). "KDM1A expression also directly correlated with tumour size, lymphatic and vascular invasion, nodal and distant metastases and advanced tumour stage." (PMID 32429269, 2020). "From these data, it was possible that miR-542-3p acted as a tumor suppressor, and KDM1A as well as ZNF346 exerted oncogenic function." (PMID 33987474, 2020). "To further investigate the effect of KDM1A on tumour metastasis, we performed pulmonary metastasis assay in nude mice by injecting sh‐KDM1A and sh‐NC transfected PTC cells through tail vein." (PMID 31211500, 2019). "In fact, KDM1A affects tumour characteristics by regulating H3K4me2 or H3K9me2.50, 51 Here, we found that the global protein levels of H3K4me2 and H3K9me2 were up‐regulated after si‐KDM1A transfection." (PMID 31211500, 2019). "In our study, we found that a treatment with a KDM1A inhibitor (2-PCPA) reduced tumor cell proliferation, migration, and invasion." (PMID 27058897, 2016).